LIN28B (lin-28 RNA binding posttranscriptional regulator B)
Diseases named in the same sentence as LIN28B in open-access papers (continued):
Sharing a sentence is not in itself a finding about the gene and the disease.
intestinal tumors (2 papers, 2018 to 2023). "Analysis of intestinal tumors from VilCre Lin28bhi mice showed that the tumors with higher LIN28B expression had higher CLDN1 expression when compared with tumors from VilCre Lin28blo mice." (PMID 37318881, 2023).
myeloid leukemia (2 papers, 2021 to 2025). A clonal proliferation of myeloid cells and their precursors in the bone marrow, peripheral blood, and spleen. "LIN28B expression is characteristic of myeloid leukemias, and might be argued that its expression represents an immature proliferative state." (PMID 33989517, 2021).
oesophageal cancer (2 papers, 2012 to 2020). "In the present study, Lin28B expression was significantly associated with the invasive activity of oesophageal cancer cells." (PMID 22433967, 2012). "In vitro studies confirmed that Lin28B expression was associated with aggressiveness of oesophageal cancer through increased proliferation and invasive activities in oesophageal cancer cells." (PMID 22433967, 2012). "Moreover, in vitro studies confirmed that Lin28B expression was associated with aggressiveness of oesophageal cancer by increasing the proliferation and invasiveness of oesophageal cancer cells." (PMID 22433967, 2012). "A clinical study found that LIN28A and LIN28B were overexpressed in oesophageal cancer cells, especially on the invasive front." (PMID 32828126, 2020). "Further studies are required to elucidate the roles of Lin28/Lin28B and let-7 network in oesophageal cancers." (PMID 22433967, 2012). "In another oesophageal cancer cell line, TE-10, the reduced proliferation and invasive activity of Lin28B-knockdown cells were confirmed." (PMID 22433967, 2012). "First, we screened several oesophageal cancer cell lines, and found that some cell lines express Lin28B, while expression of Lin28 is quite low in all cell lines examined (data not shown)." (PMID 22433967, 2012). "Lin28 and Lin28B expression was examined by immunohistochemistry in 161 tissues from patients with oesophageal cancer who had undergone curative surgery." (PMID 22433967, 2012). "Further studies are needed to confirm the role of feedback loops including Lin28/Lin28B and let-7 in oesophageal cancer." (PMID 22433967, 2012). "In this study, we analysed the expression of Lin28 and Lin28B, a homologue of Lin28, in oesophageal cancer by immunohistochemistry and determined the relationship between their expression and various clinicopathological parameters including prognosis of patients." (PMID 22433967, 2012). "Thus, to study the effects of expression of Lin28B on cellular proliferation, its expression was knocked down by transfecting si-Lin28B in TE-13 oesophageal cancer cells." (PMID 22433967, 2012). "First, we determined the expression pattern of Lin28 and Lin28B in cancerous and non-cancerous tissues from patients with oesophageal cancer." (PMID 22433967, 2012). "In the present study, Lin28B expression correlated inversely with let-7 expression in oesophageal cancer cell line and human oesophageal cancers, although no such correlation was identified between Lin28 and let-7 expression." (PMID 22433967, 2012). "Lin28 and Lin28B were overexpressed in oesophageal cancer cells compared with non-cancerous epithelial cells, especially in the invasive front." (PMID 22433967, 2012). "We found significant relationship between let-7 expression and Lin28B expression, but not Lin28 expression in the surgical specimens of oesophageal cancer." (PMID 22433967, 2012).
oral cavity cancer (2 papers, 2019 to 2020). A primary or metastatic malignant neoplasm involving the oral cavity. "Zhang et al46 found LIN28B rs221636 could decrease the risk of oral cavity cancer in a study of 384 cases and 731 healthy controls, including six SNPs in let‐7/LIN28 gene." (PMID 31747721, 2020).
osteosarcoma (2 papers, 2024). A usually aggressive malignant bone-forming mesenchymal neoplasm, predominantly affecting adolescents and young adults. "Recent studies have found that LIN28B promotes aerobic glycolysis and reduces oxidative phosphorylation in osteosarcoma cells." (PMID 38565547, 2024).
squamous cell carcinoma (2 papers, 2020 to 2021). A carcinoma arising from squamous epithelial cells. "Since MYCT58A expression drove increased expression of the stem cell markers Lin28B, Lgr6, and Sox2 in this model, we also asked if the expression of these genes correlated in human squamous cell carcinomas." (PMID 32895364, 2020). "By the way, an upregulation of LIN28B was also observed in metastatic lymph node; deleting LIN28B could attenuate oncogenicity of human gingival epithelial cell line (SG) and hypopharyngeal squamous cell carcinoma cell line (FaDu), and both of which were OSCC cells." (PMID 34353342, 2021).
abortion (1 paper, 2021). the ending of pregnancy by removing a fetus or embryo before it can survive outside the uterus. "The low expression of LIN28B in URSA villous trophoblast cells may be one of the causes of abortion." (PMID 35118391, 2021). "This study aims to verify the role of LIN28B in trophoblastic villous tissue and cells from women with URSA (unexplained recurrent spontaneous abortion) and artificial termination of pregnancy (negative control, NC)." (PMID 35118391, 2021).
adenoma (1 paper, 2021). A neoplasm arising from the epithelium. "To assess the pattern of CDX2 expression during LIN28B-mediated tumorigenesis, we investigated the expression of CDX2 in adenomas in Vil-Lin28b mice by IHC staining." (PMID 33755595, 2021).
alcohol abuse (1 paper, 2023). The use of alcoholic beverages to excess, either on individual occasions ("binge drinking") or as a regular practice. "Furthermore, the suppression and loss of let-7 expression, which is related to alcohol abuse, promotes ALD progression and eventually carcinogenesis, due to the disruption of Lin-28 homolog B (LIN28B) gene expression." (PMID 37108330, 2023).
aortic aneurysm (1 paper, 2023). A ruptured aneurysm located in the wall of the proximal portion of the descending aorta proceeding from the arch of the aorta. "However, it is possible that LIN28B inhibition may increase the risk of aortic aneurysm." (PMID 37822152, 2023).
atherosclerosis (1 paper, 2023). A disease characterized by the build-up of fatty material and calcium deposition in the arterial wall resulting in partial or complete occlusion of the arterial lumen. "For instance, Sirt6 inhibits mouse vascular endothelial cell pyroptosis via modulation of Lin28b/let-7 pathway in atherosclerosis." (PMID 37497437, 2023). "Sirt6 downregulates Lin28b expression and demonstrates anti-pyroptosis effect in the inflammatory progress of atherosclerosis." (PMID 37497437, 2023).
B-cell lymphomas (1 paper, 2011). "In contrast, the expression of the miR-16 family has been shown to be suppressed >1.5-fold by c-Myc and lin28B in B-cell lymphomas, which mirrors the preliminary HBx-c-Myc-miR-15a/16 pathway found in our study." (PMID 21629246, 2011).
central nervous system primitive neuroectodermal tumors (1 paper, 2016). "Specifically, the overexpression of LIN28B has been observed in central nervous system primitive neuroectodermal tumors (PNETs) and AT/RT." (PMID 27095948, 2016).
cholestasis (1 paper, 2021). Impairment of the bile flow caused by obstruction within the liver, or outside the liver in the bile duct system. "Recently, c-Myc and LIN28B were reported to be upregulated in early steps of cholestasis accelerated CCA progression." (PMID 34837926, 2021). "Together, considering that LIN28B/IL-6/STAT3 regulation seems to be an inflammatory loop-driven CCA initiation and able to explain the function of LIN28B in an early step of cholestasis -accelerated CCA in vivo." (PMID 34837926, 2021).
choriocarcinoma (1 paper, 2022). An aggressive malignant tumor arising from trophoblastic cells. "In the study of choriocarcinoma, β-Catenin, as a critical mediator of the Wnt signaling pathway, promotes the proliferation of human choriocarcinoma cells via the LIN28B/Let-7a/IMP1 pathway which mediates inhibition of let-7a, promotes IMP1 expression and thereby promotes proliferation of JAR cells." (PMID 35706003, 2022).
chronic endometritis (1 paper, 2020). A non-granulomatous or granulomatous chronic inflammation of the endometrium. "Two SNPs of the LIN28B gene (rs314276 and rs4946651) were involved in five out of 11 most significant models of epistatic interactions, and polymorphism rs314280 LIN28B was associated with UL only through interaction with induced abortions and chronic endometritis." (PMID 33552117, 2020).
chronic hepatitis (1 paper, 2013). An active inflammatory process affecting the liver for more than six months. "The histological findings showed no obvious difference from those of the 13 non-tumor liver tissue samples without Lin28B expression, in which seven cases showed cirrhosis and 6 cases showed chronic hepatitis with interface activity." (PMID 24244607, 2013).
Cirrhosis (1 paper, 2013). A chronic disorder of the liver in which liver tissue becomes scarred and is partially replaced by regenerative nodules and fibrotic tissue resulting in loss of liver function. "Since there was low level of Lin28B expression in only two out of 15 (13%) non-tumor liver tissue samples and one of these two samples showed cirrhosis, this association may not be due to non-cirrhotic liver status itself." (PMID 24244607, 2013).
cortical dysplasia (1 paper, 2016). "The relative expression of LIN28A (3.8–156.9-fold; p = 0.009), LIN28B (4.1–76.9-fold; p = 0.012) and CCND1 (5.7–126.0-fold; p = 0.009) were higher in AT/RT tissues, compared with cortical dysplasia tissues." (PMID 27095948, 2016).
demyelinating disease (1 paper, 2015). A broad group of disorders that affect the myelin sheaths that cover the neurons. "We conclude that the Lin28B/let-7 axis acts as a critical driver of PNS myelination, in particular by regulating myelination onset, identifying this pathway also as a potential therapeutic target in demyelinating diseases." (PMID 26466203, 2015).
epithelial dysplasia (1 paper, 2015). "Our results revealed that negative or low LIN28B expression was commonly observed in normal epithelial, whereas more LIN28B abundance was identified in epithelial dysplasia and invasive SCC in the DMBA-induced OSCC animal model." (PMID 26478718, 2015). "Immunohistochemical staining of LIN28B in buccal samples from diverse stages of disease indicated negative in most normal epithelial but significantly higher in epithelial dysplasia and invasive carcinoma." (PMID 26478718, 2015).
Globozoospermia (1 paper, 2015). Any structural anomaly of the acrosome resulting in a round sperm head. "Six imprinted genes showed different 5hmC patterns between normal and abnormal sperm (GDAP1L1, GNAS, KCNK9, LIN28B, RB1, RTL1), and five imprinted genes showed different 5hmC patterns between normal and globozoospermia sperm (KCNK9, LIN28B, RB1, SLC22A18, ZDBF2)." (PMID 25762640, 2015).
Hepatitis (1 paper, 2013). Inflammation of the liver. "On this base, Lin28B mRNA was detected in 3 cases (5%) of non-HCC controls (1 in healthy group and 2 in hepatitis group) and in 32 cases (33.3%) of HCC group." (PMID 24244607, 2013).
hypogonadotropic hypogonadism (1 paper, 2015). Abnormal ovarian or testicular function due to insufficient hormonal stimulation from the hypothalamic-pituitary axis. "The dissociation of Lin28a and Lin28b expression reported here is reminiscent of the observed changes in the testicular expression of both targets a model of hypogonadotropic hypogonadism in mice." (PMID 26494358, 2015).
hypothalamic hamartoma (1 paper, 2023). "CPP may incorporate genetic alterations, such as MKRN3, DLK1, and KISS1; mutations in the epigenetic factors that regulate the HPG axis, such as Lin28b and Let 7; syndromes; central lesions such as hypothalamic hamartoma; and others." (PMID 38021712, 2023).
hypothyroidism (1 paper, 2015). Abnormally low levels of thyroid hormone. "For this reason, we studied testicular expression of Lin28a and Lin28b mRNAs and let-7a, let-7b, mir-145 and mir-132 miRNAs in models of GH deficiency, hypothyroidism and in adrenalectomized rats." (PMID 26494358, 2015).
juvenile myelomonocytic leukemia (1 paper, 2016). A myelodysplastic/myeloproliferative neoplasm of childhood that is characterized by proliferation principally of the granulocytic and monocytic lineages. "More recently, high LIN28B expression was associated with elevated levels of HbF in patients with juvenile myelomonocytic leukemia, thus identifying expression of LIN28B as the hallmark of a novel fetal-like molecular subgroup in this disease." (PMID 27861570, 2016).
liver fibrosis (1 paper, 2023). "Decreased Col1a1 mRNA levels as a consequence of miRNA regulation has been suggested following Lin28B (a suppressor of miRNA synthesis) knock-out in a mouse model of alcohol-induced liver fibrosis." (PMID 37373151, 2023).
Lymphatic Metastasis (1 paper, 2017). Transfer of a neoplasm from its primary site to lymph nodes or to distant parts of the body by way of the lymphatic system. "In patients, high Lin28B expression was significantly correlated with high levels of lymphatic metastasis, distant metastasis and a poor prognosis." (PMID 28947981, 2017).
lymphopenia (1 paper, 2019). Reduction in the number of lymphocytes. "To test whether let-7 miRNA expression is needed for T cell homeostasis, and whether the absence of these miRNAs can account for T cell lymphopenia in mice, we took advantage of T-cell specific lin28b transgenic (Lin28Tg) animals." (PMID 31130952, 2019).
mesenchymal tumors (1 paper, 2020). "In many other mesenchymal tumors, activated LIN28A or LIN28B RNA-binding protein homologues directly interact with the terminal loop region of either pre-let-7 and/or primary let-7, preventing their biogenesis and tumor repressive function, and can induce their degradation." (PMID 32365712, 2020).
Miscarriage (1 paper, 2021). A pregnancy that ends at a stage in which the fetus is incapable of surviving on its own, defined as the spontaneous loss of a fetus before the 22th week of pregnancy. "Our study found that the expression of LIN28B in the villous tissue of URSA patients decreased, implying that the expression of the parental imprinting gene LIN28B may inhibit the development of trophoblast cells and lead to the occurrence of miscarriage." (PMID 35118391, 2021). "LIN28B plays an important role in maintaining early pregnancy by promoting the invasion of villous cells, inhibiting apoptosis and fusion, and the reduction of LIN28B expression may lead to the occurrence of early miscarriage." (PMID 35118391, 2021).
myelofibrosis (1 paper, 2019). A partial or complete replacement of the bone marrow stroma by fibrous tissue. "Of note, Lin28b, but not Plag1, was also demonstrated to be up-regulated following loss of Ezh2 during the accelerated development of Jak2V617F-mediated myelofibrosis." (PMID 30890554, 2019).
neuroendocrine prostate tumors (1 paper, 2025). "Using DuNE cells to model therapy-induced neuroendocrine prostate tumors, we observed that Lin28b specifically localizes to SGs, as evidenced by its co-localization with SG markers G3BP1 and YB-1, but not with DCP1, a P-body biomarker, under stress conditions." (PMID 39800739, 2025).
Obesity (1 paper, 2025). Accumulation of substantial excess body fat. "In addition, epigenetic changes, such as polymorphisms in the MKRN3 and LIN28B genes, as well as prenatal and postnatal environmental factors, intestinal microbiota, and endocrine disruptors, are also associated with the adolescent development of children and adolescents with obesity." (PMID 40150457, 2025).
ovarian epithelial tumor (1 paper, 2018). A benign, borderline, or malignant tumor that originates from the surface epithelium of the ovary. "Importantly, LIN28B was undetectable in either the normal human ovarian surface or the fallopian tube epithelia, from which ovarian epithelial tumors may be derived." (PMID 30174831, 2018).
ovarian tumours (1 paper, 2011). "Knockdown of LIN28 and LIN28B expression resulted in re-expression of Let-7 providing additional evidence of a chain of interactions in ovarian tumours." (PMID 21533284, 2011).
peripheral T cell lymphomas (1 paper, 2019). "Overexpression of Lin28b in transgenic mice results in peripheral T cell lymphomas with a relatively lengthy latency, while Plag1 overexpression alone does not induce disease, so neither alone were predicted to cause AML." (PMID 30890554, 2019).
prostate adenocarcinoma (1 paper, 2014). "Similarly, we found Lin28B is expressed in prostate adenocarcinomas (irrespective of Gleason grade) but not in the glands of normal prostate tissue." (PMID 25201220, 2014).
prostate tumors (1 paper, 2019). "The expressions of Lin28A and Lin28B enhance PCa stemness and tumorigenesis via the downregulation of Let-7 miRNA, suggesting that the deregulation of Lin28A and Lin28B/Let-7 miRNA axes promotes the acquisition of tumorigenic and CSC-like properties in prostate tumors." (PMID 31530793, 2019).
renal fibrosis (1 paper, 2024). A final common manifestation of a wide variety of chronic kidney diseases characterized by glomerulosclerosis and tubulointerstitial fibrosis. "LIN28B was also shown to be involved in renal fibrosis in DN." (PMID 38966710, 2024).
retinal degeneration (1 paper, 2016). Degeneration of the retina. "We found that Lin28B expression only increased before retinal degeneration at p1 and p7 in RCS-p+ rat retinas compared with controls." (PMID 27384999, 2016). "We proposed that upregulating Lin28B might repress overexpression of let-7e and let-7i in the Müller cells during retinal degeneration, thereby tightly controlled their de-differentiation and proliferation." (PMID 27384999, 2016).
testicular tumors (1 paper, 2022). "LIN28A and LIN28B might present potential targets for developing new therapies in the treatment of fertility but also testicular tumors." (PMID 35806250, 2022).
undifferentiated carcinoma (1 paper, 2014). A usually aggressive malignant epithelial neoplasm composed of atypical cells which do not display evidence of glandular, squamous, or transitional cell differentiation. "Two prostate tissue arrays T191 and PR243a from US Biomax, Inc., which includes normal prostate control tissues, well to poorly differentiated adenocarcinomas and undifferentiated carcinoma were used to identify the expression of Lin28B." (PMID 25201220, 2014).